EZH2 (enhancer of zeste 2 polycomb repressive complex 2 subunit)
Diseases named in the same sentence as EZH2 in open-access papers (continued):
Sharing a sentence is not in itself a finding about the gene and the disease.
hepatocellular carcinoma (continued). "The knockdown of UCA1 in hepatoma cells decreased the binding of EZH2 and H3K27me3 on the p27 promoter and significantly suppressed tumor growth in a xenograft mouse model." (PMID 34206504, 2021). "EZH2 is highly expressed in solid tumors and is involved in poor prognosis in hepatocellular carcinoma (HCC)." (PMID 32370249, 2020). "EZH2 regulating miR-139 has been reported in various diseases; for instance, EZH2 exercises its pro-metastatic role by suppressing miR-139-5p expression in hepatocellular carcinoma." (PMID 33292225, 2020). "Some studies have showed that lncRNA DLEU2 interacted with EZH2 to promote the proliferation, migration and invasion of hepatocellular carcinoma, thus accelerating the malignant progression of hepatocellular carcinoma." (PMID 32587476, 2020). "Considering that EZH2-Wnt/β-catenin axis is found in CSCs of hepatocellular carcinoma, we sought the role of Wnt/β-catenin signaling in UM CSCs." (PMID 32127003, 2020). "Correlation of EZH2 mRNA expression and prognosis in hepatocellular carcinoma with different clinicopathological factors by Kaplan-Meier plotter." (PMID 33180829, 2020). "A recent research has disclosed that sorafenib can prevent EZH2 expression by accelerating its ubiquitination-proteasome degradation in hepatoma cells." (PMID 33308321, 2020). "Hepatoma cells expressed high level of EZH2, and had only marginally increased PD-L1 expression upon IFNγ stimulation." (PMID 31727135, 2019). "To evaluate the effect of EZH2 on PD-L1 expression, we used different hepatoma cell lines treated with IFNγ, which is a potent PD-L1 induction factor in multiple tumors." (PMID 31727135, 2019). "Inhibiting EZH2 by GSK126 or DZNep treatment effectively increased IFNγ-induced PD-L1 expression in hepatoma cells." (PMID 31727135, 2019). "In the present study, we reported that the epigenetic modifier EZH2 negatively regulated IFNγ-induced PD-L1 expression in hepatoma cells." (PMID 31727135, 2019). "In the present study, we provided evidence from clinical samples and in vitro cellular experiment that hepatoma-intrinsic EZH2 represses the expression of PD-L1." (PMID 31727135, 2019). "One protein member of this pathway, MDM2 Proto Oncogene (MDM2), was stabilized by PVT1 via its interaction with Enhancer Of Zeste 2 Polycomb Repressive Complex 2 Subunit (EZH2) in the setting of hepatocellular carcinoma." (PMID 31710657, 2019). "In vitro cell experiments revealed that EZH2 negatively regulated the PD-L1 expression of hepatoma cell lines in IFNγ-dependent manner." (PMID 31727135, 2019). "In the present study, we found that hepatoma cells expressed high levels of EZH2, which abrogated PD-L1 upregulation by IFNγ." (PMID 31727135, 2019). "Immunoblotting assays showed that the effective EZH2-targeted siRNAs enhanced IFNγ-induced PD-L1 expression in hepatoma cell." (PMID 31727135, 2019). "Rh2 also suppresses proliferation of hepatocellular carcinoma (HCC) cells by targeting EZH2 to regulate CDKN2A-2B gene cluster transcription." (PMID 31780945, 2019). "HBV-associated chromatin modifying enzymes of PCAF, p300/CBP, HDAC1, SIRT1, and EZH2 have been shown to bind to the cccDNA in human hepatoma cells containing replicating HBV49." (PMID 30115977, 2018). "In the MHCC97H and MHCC97L cells lines (hepatocellular carcinomas), lncRNA Carlo5 bound to EZH2 protein and recruited it onto the miR-200b promoter to repress its transcription." (PMID 34991274, 2018). "It has been reported that the enhancer of zeste homologue 2 gene (Ezh2) was targeted by miR-214 in mouse skeletal muscle and embryonic stem cells and in human hepatocellular carcinoma." (PMID 28076844, 2017). "miR-214 was found to regulate the polycomb protein Ezh2 in skeletal muscle and embryonic stem cell, and suppress stem-like traits in human hepatocellular carcinoma though targeting beta-catenin pathway." (PMID 28186995, 2017).
hepatocellular carcinoma (continued). "Here, the authors demonstrate that CXRC4 is overexpressed in hepatocellular carcinoma and is associated with poor prognosis and, mechanistically CXCR4 is increased in expression via EZH2 repression of microRNA-622." (PMID 26404566, 2015). "For example, the oncogenes ROCK2 and EZH2 that are direct targets of tumor-suppressive miR-124 in hepatocellular carcinoma, and the IQGAP1 who is directly repressed by miR-124 in HCC cell lines and plays important functions in the cell adhesion and motility." (PMID 25069957, 2014). "EZH2 was also reported to silence miR-139-5p through H3K27 methylation in human hepatocellular carcinoma." (PMID 24885920, 2014). "Recent studies showed that expression of Ezh2 is correlated with the worse outcome of patients with hepatocellular carcinoma (HCC), and regulates proliferation and tumorigenicity of tumor-spheres derived from HCC cell lines." (PMID 25153170, 2014). "The over-expression of EZH2 has been described in various types of cancers, including prostate, breast, bladder, gastric, lung, and hepatocellular carcinoma, which correlate with aggressive clinical manifestations." (PMID 25431950, 2014). "To evaluate the diagnostic value of this protein in hepatic tumors we have investigated the presence of EZH2 by immunohistochemistry in hepatocellular carcinomas and other common hepatic tumors." (PMID 22809481, 2012). "Recently, enhancer of zeste homologue 2 (EZH2), a new marker for hepatocellular carcinomas has been described." (PMID 22809481, 2012). "Our immunostainings confirm that EZH2 is a sensitive marker of hepatocellular carcinoma, but its specificity is very low, since almost all the investigated malignant liver tumors were positive regardless of their histogenesis." (PMID 22809481, 2012). "Additionally, epigenetic silencing of ZIC4 by enhancer of zeste homolog 2 (EZH2) mediated H3K27 trimethylation (H3K27me3) was described in hepatocellular carcinoma (HCC)." (PMID 40952541, 2025). "In addition, DLEU2 promotes cancer cell proliferation by interacting with EZH2 in hepatocellular carcinoma (HCC)." (PMID 37095423, 2023). "Similarly, a study that investigated CSPG5 and the prognosis of hepatocellular carcinoma indicated that CSPG5 is related to the transcription factors EZH2 and B-Myb, which reportedly play critical roles in EMT and cell cycle progression." (PMID 37443739, 2023). "Deleted in lymphocytic leukemia 2 (DLEU2) was able to directly interact with Hepatitis B protein and enhancer of zeste 2 polycomb repressive complex 2 subunit (EZH2), leading to transcriptional activation of a subset of genes related to hepatocellular carcinoma." (PMID 37036576, 2023). "Moreover, we analysed the correlation between EZH2 expression levels and different molecular subtypes in hepatocellular carcinoma." (PMID 35659256, 2022). "Furthermore, EZH2 has been shown to suppress immune evasion of hepatocellular carcinoma cells by recruiting H3K27me3 to promoter and negatively affect programmed death-ligand 1 (PD-L1) expression." (PMID 35236381, 2022). "However, systemic overexpression of EZH2 was significantly associated with impaired effector memory CD8+ T cell infiltration and poor survival in patients with hepatocellular carcinoma." (PMID 34737746, 2021). "Moreover, lncRNA UCA1 is physically linked to the enhancer of zeste homolog 2 (EZH2), which inhibits p27Kip1 through histone methylation (H3K27me3) in p27Kip1 promoter, thus promoting tumorigenesis in nude mice in hepatocellular carcinoma." (PMID 34868904, 2021). "The enhancer of zeste homologue 2 (EZH2) is a recently used marker for hepatocellular carcinomas, but it can also be used in the treatment of cholangiocellular carcinomas as it is able to differentiate between neoplastic or benign (or reactive) biliary proliferation." (PMID 33743673, 2021). "It is universal that EZH2 positively regulates Wnt/β-catenin signaling in hepatocellular carcinoma." (PMID 32127003, 2020).
hepatocellular carcinoma (continued). "The EZH2/miR-26 feedback loop can regulate tumor growth in hepatocellular carcinoma." (PMID 33718109, 2020). "Interestingly, miR-22 was reported to be repressed by enhancer of zeste homolog 2 (EZH2) in hepatocellular carcinoma." (PMID 32657761, 2020). "In hepatocellular carcinoma, EZH2 can inhibit the expression of miR-22 through H3K27me3 pathway." (PMID 33718109, 2020). "EZH2 has also been shown to promote hepatocellular carcinoma progression." (PMID 32699528, 2020). "PVT1 was reported to bind EZH2 and improve the EZH2 protein stability in hepatocellular carcinoma." (PMID 33763107, 2020). "A prior study documented the ability of EZH2 to repress miR-22 in hepatocellular carcinoma." (PMID 32657761, 2020). "In this study, we observed that downregulating the EZH2 could enhance IFNγ-induced PD-L1 expression in hepatoma cells." (PMID 31727135, 2019). "On the basis of our previous finding that EZH2 feedback regulates miR-101 in hepatocellular carcinoma, we hypothesized that O-GlcNAcylation provides feedback that regulates miR-101 by H3K27me3 in CRC." (PMID 30093632, 2019). "Furthermore, qPCR, immunoblotting, and flow cytometry analyses confirmed that IFNγ-induced PD-L1 expression was upregulated in a variety EZH2-silenced hepatoma cells." (PMID 31727135, 2019). "Taken together, our data revealed that EZH2 acts as an intrinsic modifier that could influence PD-L1 expression in hepatoma cells." (PMID 31727135, 2019). "Using the same approach, several cellular transcription factors (CREB, ATF, YY1, STAT1, and STAT2) and chromatin modifying enzymes (PCAF, p300/CBP, HDAC1, SIRT1, and EZH2) have been shown to bind to the cccDNA in human hepatoma cells containing replicating HBV." (PMID 24133502, 2013). "Recently, we have also reported that EZH2 epigenetically inactivates expressions of multiple tumor and metastasis suppressor microRNAs (miRNAs), such as miR-125b and miR-139 in human hepatocellular carcinoma (HCC), thereby promotes HCC tumorigenicity and metastasis." (PMID 23826380, 2013). "It was reported that miR-26a, miR-98, miR-101, miR-124, miR-138 and miR214 inhibit the expression of EZH2 in nasopharyngeal carcinoma, nasopharyngeal carcinoma, glioblastoma, hepatocellular carcinoma, head and neck squamous cell carcinoma, and neuroblastoma, respectively." (PMID 22867052, 2012). "We thus analysed EZH2 expression using real-time reverse transcription–polymerase chain reaction, and correlated its expression status with various clinicopathological parameters in 66 patients with hepatocellular carcinoma (HCC)." (PMID 15856046, 2005). "Additionally, miR-142 targets ASH1L/KMT2H in leukemia and thyroid cancer, miR-675 regulates SUV39H2/KMT1B in liver cancer, miR-122 influences SUV39H1/KMT1A in hepatocellular carcinoma, and miR-101 modulates KMT6/EZH2 in non-small cell lung cancer (NSCLC), prostate, and renal cancers." (PMID 40761244, 2025). "In this study, we revealed that UPF1 regulates the abundance of hepatocellular carcinoma upregulated EZH2-associated lncRNA (lncRNA-HEIH) by binding the CG-rich motif, thereby regulating hepatocellular carcinoma (HCC) tumorigenesis." (PMID 38297160, 2024). "Additionally, a separate study found that a structural derivative of emodin, emodin succinyl ester (ESE), inhibits malignant proliferation and migration of hepatocellular carcinoma by suppressing the interaction between androgen receptor (AR) and enhancer of zeste homolog 2 (EZH2)." (PMID 38892575, 2024). "Besides, miRNA/EZH2 axis can regulate the response of hepatocellular carcinoma cells to therapy." (PMID 35236381, 2022). "Indeed, we observed a decrease in H3K27me3 and cell proliferation concordant with Doxycycline concentration, which was consistent with previous report that EZH2 could be a potential oncogene in Hepatocellular carcinoma." (PMID 36185457, 2022).
hepatocellular carcinoma (continued). "HOTAIR negatively regulates miR-218 expression in hepatocellular carcinoma (HCC) cells through an EZH2-miR-218-2 promoter regulatory axis, and this functional interaction increases cell growth and proliferation." (PMID 33540611, 2021). "The upstream signaling protein of DNMTis, enhancer of zeste two polycomb repressive complex two subunits (EZH2), downregulated PD-L1 expression in hepatocellular carcinoma (HCC)." (PMID 34088360, 2021). "EZH2‐mediated H3K27me3 was involved in the repression of ZIC4 in HCC cell lines for the first time, which provided a new therapeutic target for the treatment of hepatocellular carcinoma disease." (PMID 33097694, 2020). "In addition, PVT1 was shown to bind EZH2 and improve its stability in hepatocellular carcinoma." (PMID 33763107, 2020). "In hepatocellular carcinoma, the inhibition of EZH2 by small-molecule or genetic inhibitors can enhance HCC cell eradication by NK cells in an NK group 2D (NKG2D) ligand-dependent manner." (PMID 33180829, 2020). "Moreover, knockdown of IRF1 in EZH2-silenced hepatoma cells decreased the abundance of PD-L1." (PMID 31727135, 2019). "We aimed to figure out the molecular network of PVT1 and EZH2 on hepatocellular carcinoma (HCC) cells growth." (PMID 30008615, 2018). "To confirm our hypothesis, we performed EZH2 overexpression and knockdown in hepatoma cells." (PMID 26404566, 2015). "EZH2 up-regulation was frequently detected in hepatocellular carcinoma (HCC) suggesting its potential role as a sensitive malignancy marker in this tumour." (PMID 24351808, 2013). "For instance, miR-139-5p, miR-125b, miR-101, let-7c, miR-200b were found to be epigenetically repressed by EZH2, and miR-449 was repressed by HDACs in human hepatocellular carcinoma (HCC)." (PMID 24261995, 2013). "For instance, miR-29a targets the MYC/HDAC3/EZH2 axis in lymphoma, while miR-200a regulates HDAC4 and SP1 in hepatocellular carcinoma." (PMID 40761244, 2025). "For example, in Nonalcoholic Fatty Liver Disease (NAFLD)-related Hepatocellular Carcinoma (HCC), HDAC8 and EZH2 regulated H4ac content and H3K27me3 levels of the AXIN2 gene, respectively." (PMID 39719443, 2024). "Traditional histopathological examinations are insufficient to accurately predict hepatocellular carcinoma (HCC) survival; however, pathomics models can predict EZH2 expression and HCC prognosis." (PMID 39640777, 2024). "Recently, it has also been found that acquired resistance toward Infigratinib in hepatocellular carcinoma correlates with higher phosphorylation levels of ERBB2/3 and increased EZH2 expression." (PMID 38177929, 2024). "The expression of PD-L1 was suppressed by epigenetic modificator EZH2 via directly upregulating the promoter H3K27me3 levels of CD274 and IRF1 in hepatoma cells." (PMID 37056572, 2023). "Findings from in vitro studies also affirm that curcumin can upregulate the enhancer of zeste homolog 2 (EZH2) breast cancerous cells and downregulate deletion gene 1(DLC1) in hepatocellular carcinoma." (PMID 36839961, 2023). "In hepatocellular carcinoma, IGFBP4 as a novel tumor suppressor potently inhibits cell proliferation, invasion, and diminishes xenograft tumor growth in mice by the EZH2 and AKT pathways." (PMID 37433992, 2023). "Molecularly, it was shown that EZH2 silences Wnt antagonists, such as DKK1 and AXIN2, leading to Wnt/β-catenin signaling activation in hepatocellular carcinoma." (PMID 37175580, 2023). "Among the prognostically characterized aging genes, EZH2, G6PD, LGALS3 and PSMD14 were significantly differentially expressed in hepatocellular carcinoma samples from the TCGA database." (PMID 37853322, 2023). "Enhancer of zeste homolog 2 (EZH2) is a histone methyltransferase involved in cell proliferation, invasion, angiogenesis, and metastasis in various cancers, including hepatocellular carcinoma (HCC)." (PMID 36071871, 2022). "We found that H19 was specifically bound by EZH2 and JARID2 in hepatoma cell lines and repressed in HCC patients." (PMID 36578923, 2022).
hepatocellular carcinoma (continued). "MiRNA-138 reduces EZH2 expression to inhibit EMT, resulting in an increase in cisplatin sensitivity in hepatocellular carcinoma cells." (PMID 35236381, 2022). "EZH2 activates trimethylation of miRNA-622 promoter at H3K27 to diminish its expression, leading to CXCR4 upregulation and increased progression of hepatocellular carcinoma." (PMID 35236381, 2022). "Studies have revealed that EZH2 elevates hepatocyte growth factor (HGF) and macrophage migration inhibitory factor (MIF) in hepatocellular carcinoma, which contribute to M2 repolarization and poor prognosis." (PMID 36038549, 2022). "In hepatocellular carcinoma, circ-LRIG3 enhances EZH2 expression and induces STAT3 methylation to promote cancer progression." (PMID 35236381, 2022). "In hepatocellular carcinoma, IFN-γ enhances the expression level of miRNA-26a that subsequently, down-regulates EZH2 to suppress metastasis." (PMID 35236381, 2022). "For example, LINC01419 targets enhancer of zeste homolog 2 (EZH2) to hinder the expression of RECK and heighten cell proliferation, migration and invasion in hepatocellular carcinoma." (PMID 34790697, 2021). "Through binding with EZH2 to inhibit E-cadherin expression, CTD-3252C9.4 contributes to hepatocellular carcinoma cell invasion and migration." (PMID 34399768, 2021). "Circ-LRIG3 interacts with EZH2 and STAT3 to facilitate EZH2-induced STAT3 phosphorylation, resulting in the malignant progression of hepatocellular carcinoma." (PMID 34485151, 2021). "For instance, HNF1A-AS1 promotes hepatocellular carcinoma cell proliferation by repressing the NKD1 and p21 expression via interacting with EZH2, or by sponging miR-30b-5p to promote autophagy." (PMID 33024199, 2020). "Altogether, these data indicate that epigenetic silencing of ZIC4 by EZH2 mediated H3K27me3 is an important mechanism in HCC and provide a new therapeutic target for the treatment of hepatocellular carcinoma disease." (PMID 33097694, 2020). "A concentration gradient of DZNep (an inhibitor of all S­adenosyl­methionine (SAM)­dependent enzymes, including EZH2) and GSK126 (a selective inhibitor of EZH2 methyltransferase activity) were applied to reprogram the epigenetic pathways in hepatoma cells." (PMID 31727135, 2019). "Overexpression of miR-124 inhibits aggressiveness of hepatocellular carcinoma cell by targeting ROCK2 and EZH2." (PMID 24279510, 2013). "The expression level of EZH2 in hepatocellular carcinoma (HCC) is highly correlated with tumor progression; however, it has not been determined if specific EZH2 genetic variants are associated with the risk of HCC." (PMID 24040354, 2013). "Our study also provided first experimental evidence to show that induction of endogenous miR-101 indeed is accompanied with lower EZH2, EED and SUZ12 level and histone 3 lysine 27 trimethylation in human hepatoma cells." (PMID 20444294, 2010). "Notably, the expression levels of certain genes, such as ANXA2 and EZH2, were significantly elevated in HCC tumor tissues, further underscoring their importance in hepatocellular carcinoma development." (PMID 40018411, 2025). "In hepatocellular carcinoma, combined knockdown of EZH1 and EZH2 has shown greater tumor suppression than targeting EZH2 alone, suggesting that dual inhibitors could be more effective in certain cancers." (PMID 40042761, 2025). "We treated the HUH-7 cells, established from male hepatoma tissue, with palmitic acid (PA) at a concentration of 100 μM for 24 h in the presence or absence of the EZH2 inhibitor EPZ-6438 at 3.3 μM." (PMID 39408226, 2024). "EZH2 recruited DNMT3A to the promoter of ULBP1, increasing DNA methylation and thus down-regulating the expression of NKG2D ligands to resist NK-cell-mediated cytotoxicity in hepatoma cells." (PMID 37268997, 2023). "Similarly, in hepatocellular carcinoma (HCC), FOXP4-AS1 can also accelerate HCC progression by recruiting EZH2 to suppress ZC3H12D expression." (PMID 35720005, 2022).